U8 (U8 small nucleolar RNA )
Synonyms: LOC124900318
Gene: Small nucleolar RNA gene on chromosome 12 (103,592,112 to 103,592,243, forward strand). Ensembl gene ENSG00000212594.
Gene Ontology:
Biological process: RNA processing
Cellular component: nucleolus
Homologues: Orthologues: chimpanzee U8 (99% identical), macaque U8 (89% identical), guinea pig U8 (76% identical). Paralogues in human: U8 (80% identical), U8 (78% identical), U8 (77% identical), U8 (76% identical), U8 (74% identical), U8 (73% identical), U8 (72% identical), U8 (71% identical), U8 (70% identical), U8 (69% identical), U8 (68% identical), U8 (67% identical), and 2 more.